INS (insulin)
Diseases named in the same sentence as INS in open-access papers (continued):
Sharing a sentence is not in itself a finding about the gene and the disease.
diabetes (continued). "Because diabetes and obesity may share some characteristics, such as defective insulin signaling, and oxidative stress or inflammation, we aimed to understand the teratogenic effects of maternal obesity." (PMID 34439421, 2021). "In clinical trials, MGF treatment was already found to improve metabolic health (diabetes, hyperlipidemia, insulin resistance) by optimization of mitochondrial bioenergetic pathways (fuel switching between fatty acid and carbohydrates) via sirtuin (SIRT) and PPAR (in)dependent metabolic mechanisms." (PMID 34924998, 2021). "The genes annotated to the top 500 Cu-related CpG sites were enriched in five significant KEGG pathways (FDR < 0.01), including insulin signaling pathway, type 2 diabetes mellitus, amyotrophic lateral sclerosis, calcium signaling pathway, and purine metabolism." (PMID 33499918, 2021). "Hepatic insulin clearance, a physiological process that in response to nutritional cues clears ~50–80% of circulating insulin, is emerging as an important factor in our understanding of the pathogenesis of type 2 diabetes mellitus (T2DM)." (PMID 33668109, 2021). "Insulin is highly recommended for diabetes management in persons with liver cirrhosis." (PMID 34118892, 2021). "Most of these genes are related to immune functions and their identification allowed many cellular pathways to be recognized as pivotal for diabetes development, such as insulin gene expression in the thymus, regulation of T-cell activation and viral responses." (PMID 34681954, 2021). "Furthermore, hyperglycemia in diabetes is traditionally attributed to reduced INS sensitivity in skeletal muscle and liver but also coupled to decreased INS secretion by the pancreas." (PMID 33815298, 2021). "In addition to insulin therapy, proper nutrition and exercise play a significant role in diabetes treatment." (PMID 34836071, 2021). "Evidence has suggested that creatine supplementation alone, and mainly in combination with exercise training, may improve glucose metabolism in health individuals and insulin-resistant individuals, such as in those with type 2 diabetes mellitus." (PMID 33572228, 2021). "The impairment in β‐cell insulin secretion may worsen pre‐existing diabetes or determine the appearance of hyperglycaemia in cases of non‐diabetes." (PMID 34277995, 2021). "Moreover, patients with diabetes also face difficulties in procuring medicines including insulin as well as dressings because of interrupted supplies in the COVID-19 pandemic." (PMID 33956847, 2021). "Overall, our findings support that the insulinemic potential of diet and lifestyle may influence the incidence of diabetes in adults through mechanisms involving insulin signaling pathways." (PMID 33892738, 2021). "Because diabetes is known to increase the risk of stroke, we first examined the association of brain insulin signaling in persons with and without diabetes with the most common underlying pathology of the clinical syndrome of stroke, brain infarcts." (PMID 33858515, 2021). "Risk factors for stroke include high blood pressure, hypertension, diabetes, insulin, heart disease, cardiomyopathy, heart failure, atrial fibrillation, blood clot, smoking, cocaine, amphetamines, sickle cell disease, vasculitis, bleeding, overweight, stress, and cholesterol." (PMID 34047699, 2021). "These agents are utilized in patients with diabetes since they act freely on insulin." (PMID 34683861, 2021). "Insulin treatment may increase mortality and severe/critical complications in patients with COVID-19 and diabetes, but more large-scale studies are needed to confirm and explore the exact mechanism." (PMID 34367067, 2021). "It is conceivable that there is a subset of people who develop diabetes due to insufficient compensatory reduction of insulin clearance in response to insulin resistance, while a different subset develops insulin resistance due to hyperinsulinemia caused by low insulin clearance." (PMID 34206745, 2021).
diabetes (continued). "The diabetes control in subjects using insulin for the treatment study (DIAINFORM) showed that the frequency of acceptable metabolic control (HbA1c <7% (53 mmol/mol)) in patients with T2D treated with insulin was 37.1%." (PMID 34371848, 2021). "Besides, serine phosphorylation of IRS1 is common in both AD and diabetes, and antidiabetic agents restore normal hippocampal formation responses to insulin in the IR–IRS-1–PI3K–Akt pathway." (PMID 34975451, 2021). "Uncovering these insulin- and FoxO- regulated pathways provides insights into mechanism by which diabetes alters muscle metabolic function and new targets for improving muscle strength and preventing disability in patients with diabetes." (PMID 35185597, 2021). "It is worthy of note that although their diabetes was relatively well-controlled, subjects enrolled in this study were heavily treated with other agents both before and during the study period, most commonly metformin, insulin, and GLP-1 agonists." (PMID 34535644, 2021). "The high levels of glucose or insulin in the lungs promote the proliferation and differentiation of fibroblasts, resulting in collagen deposition and airway remodeling, contributing to the reduction of lung function in patients with diabetes." (PMID 33520042, 2021). "Given that preventing readmission is a key component of diabetes care for inpatients, TyG index could also serve as the convenient surrogate of insulin resistance to form a structured discharge plan for those patients with high risk of complications." (PMID 34671683, 2021). "In summary, EXPLODE is a single-centre feasibility randomised parallel group trial investigating whether resistance exercise training has the potential to improve the health of older people living with insulin treated diabetes." (PMID 34880011, 2021). "For example, when planning is affected, diabetes self-management could move to a more fixed insulin scheme requiring a regular eating behavior, removing the necessity for excessive planning." (PMID 36994333, 2021). "The classic clinical manifestation of diabetes is hyperglycemia, i.e. a high glucose concentration in the blood due to the altered insulin sensitivity, which exposes tissues to long-term high concentrations of sugar, consequent macro/micro-vascular pathologies and multi-organ damage." (PMID 34258010, 2021). "Insulin is one of the main therapies used to treat diabetes mellitus." (PMID 33947913, 2021). "Noteworthy, any relevant difference in QTc interval prolongation during hypoglycemia between high-risk, insulin-treated patients with type 2 diabetes and controls without diabetes does not appear to exist." (PMID 34085953, 2021). "When diabetes medications use were examined, metformin was the most frequently reported (66.5%), followed by other medications, which included thiazolidinediones and sulfonylureas (36.8%) and insulin (23.4%)." (PMID 34565341, 2021). "Diabetes mellitus (DM) is a chronic noninfectious disease which is caused by abnormal secretion or abnormal function of insulin." (PMID 33841825, 2021). "Chronic malnutrition, as indicated by low prior and current BMI, may contribute to diabetes through low insulin secretion." (PMID 33740034, 2021). "Three hundred eleven participants (5%) with diabetes were taking insulin." (PMID 34216216, 2021). "Studies concerning the effects of etanercept on insulin sensitivity, which is a pivotal factor during the onset of metabolic syndrome and diabetes mellitus, show that etanercept has a positive effect on improving fasting glucose levels by attenuating insulin resistance." (PMID 34803716, 2021). "In such patients, the glycaemic control homeostasis could already be compromised at baseline due to genetic and lifestyle-related factors, and even a mild autoimmune reaction could lead to insufficient insulin action and development of clinical diabetes." (PMID 33331974, 2021).
diabetes (continued). "Those with lower educational achievement may be less likely to understand aspects of diabetes management including but not limited to education about insulin therapy, diet, blood glucose monitoring and physical activity in T1DM." (PMID 33855206, 2021). "However, the eligibility criteria for insulin pump coverage required by the Centers for Medicare & Medicaid Services (CMS) discount conclusive evidence that supports insulin pump use in diabetes populations that are currently deemed ineligible." (PMID 34077674, 2021). "Additionally, the HFD and STZ treatment significantly decreased insulin levels in the blood (P < 0.05) and impaired insulin sensitivity, indicating that diabetes induced systemic metabolic abnormities in diabetic mice." (PMID 33637069, 2021). "On the other hand, high protein consumption resulted in less insulin response compared to a normal protein meal, suggesting keto diets may prevent insulin resistance and be beneficial to individuals with pre-diabetes or diabetes type 2." (PMID 39087082, 2021). "Several reports have indicated that the sustained expression of MafA results in augmented β-cell mass, higher plasma insulin levels, and significantly lower plasma glucose levels, thus painting a picture of miR-30d as a promising therapeutic target for diabetes management." (PMID 34069422, 2021). "Type 1 diabetes mellitus (T1DM) is characterized by hyperglycemia due to the deficiencies in insulin hormone release, while type 2 diabetes mellitus (T2DM) is hallmarked by the failure to properly respond to insulin." (PMID 34122541, 2021). "Easily the oldest treatment for diabetes is the administration of exogenous insulin." (PMID 34822370, 2021). "Lack of insulin signaling in diabetes leads to mitochondrial dysfunction, impaired neurochemical synthesis and reduced regenerative capacity, all of which might contribute to development of diabetic neuropathy." (PMID 34319011, 2021). "At present, insulin and oral hypoglycemic agents are used to treat diabetes." (PMID 34401085, 2021). "Current treatment for diabetes failed to maintain long-term blood glucose homeostasis, resulting in insulin secretion deficiency and acute and chronic diabetic complications." (PMID 33968939, 2021). "Furthermore, rs11708067 is an eQTL in islets for both ADCY5 and the antisense transcript for ADCY5 supports the role of this SNP in impairment of insulin secretion in women with previous GDM, thus increasing the risk of diabetes postpartum." (PMID 34801028, 2021). "Diabetes mellitus occurs when the body cannot produce enough insulin or use insulin effectively." (PMID 33691685, 2021). "The role of online CGM and insulin pump platforms such as Clarity, CareLink, Diasend, and LibreView may be considerable during the pandemic as they allow individuals with diabetes teams to view CGM profiles remotely." (PMID 33512267, 2021). "Furthermore, in addition to the proposed properties of the drug, probably metformin is a surrogate marker for the shorter evolution of diabetes and better glucose control (same as sulfonylureas) compared to insulin treatment." (PMID 34513785, 2021). "The different insulin signaling genes that tended to significance and some genes that expressed fold changes ≥1.5 are discussed to discern their potential interrelations and roles in cardiovascular disease, diabetes and obesity." (PMID 35069436, 2021). "Numerous differences are observed worldwide in terms of the access to medical services, education level, approach to new insulin and diabetes technologies which could influence the observed data inhomogeneity." (PMID 34727899, 2021). "Diabetes is a metabolic disorder multifaceted by impaired carbohydrates, fat, and protein metabolism due to the lack of insulin secretion and/or increased tissue resistance to insulin." (PMID 34440028, 2021).
diabetes (continued). "Therefore, in the current study, we examined the interaction of CETP TaqB1 polymorphism with dietary insulin index and load (DII and DIL), in altering on CVD risk factors among type 2 diabetes mellitus (T2DM)." (PMID 34354158, 2021). "Baseline medication for the treatment of diabetes (sulfonylurea, insulin, or both)." (PMID 34726745, 2021). "In the past decade, many advances in diabetes technology have focused on safer and more accurate glucose measurement and insulin delivery, therefore it should be acknowledged that these technologies will be of particular advantage to those on insulin therapy." (PMID 33950566, 2021). "Likely, a good metabolic control obtained by insulin therapy in patients with T1DM may normalizes the metabolic derangements induced by insulin deficiency and attenuate the detrimental effects of diabetes on the heart." (PMID 34277669, 2021). "We, surprisingly, found the lowest irisin levels in patients with diabetes who use insulin." (PMID 35284785, 2021). "Therefore, in the current study, we assessed the correlation of insulin clearance with early dysglycemia (prediabetes and newly recognized diabetes) in the context of insulin sensitivity and insulin secretion." (PMID 34206745, 2021). "Insulin treatment increased the incidence of hypoglycemia in patients with COVID-19 and type 2 diabetes mellitus (T2DM), which may impair the glucose homeostasis and glucose control to affect the COVID-19 outcomes." (PMID 34367067, 2021). "Given the raging epidemics of obesity and diabetes, it may be worth considering parameters reflecting the insulin resistance like abdominal fat distribution to the cardiovascular risk assessment." (PMID 33918620, 2021). "One famous study investigated the effects of Packy and Marlon, which is a video game for children with diabetes where the main characters must manage their insulin levels and food intake while protecting other game characters from a rat infestation at a summer camp." (PMID 33656447, 2021). "Continuous administration of FMRP thus may improve the homeostasis of not only insulin secretion and inflammation, but also the intestinal environment in inflammatory bowel disease and type 2 diabetes mellitus." (PMID 33800583, 2021). "In addition, this inhibition reduces the absorption of carbohydrates by the digestive tract and intestines, stimulates insulin-dependent glucose uptake, and reduces inflammation, thereby improving the symptoms of diabetes." (PMID 35049867, 2021). "Moreover, in order to manage a patient’s induced or exacerbated hyperglycemia when using steroids, insulin is the preferred method in patients known with diabetes, and insulin doses are determined depending on the patient’s weight." (PMID 33920079, 2021). "Notwithstanding its significant benefits in treating diabetes, insulin therapy has many limitations, including stringent storage requirements, route of administration being an injection or a pump, which compromises patients’ compliance, and variable and fluctuating dosing requirements." (PMID 34452266, 2021). "Collectively, our findings indicated that metformin had a stronger effect on gut microbiota than insulin, while insulin treatment showed greater influence on serum metabolites, which provided novel insights into the therapeutic effects of metformin on diabetes." (PMID 35046817, 2021). "A younger age, lower education level, lack of regular exercise, a diabetes diagnosis of more than seven years, insulin treatment and albuminuria have been shown to cause uncontrolled blood glucose levels." (PMID 33915834, 2021). "Since the 19th century, our understanding of glucose regulation and the pathogenesis of diabetes has mainly been based on processes in peripheral tissues, in particular the islets of Langerhans in the pancreas and target organs of insulin action such as the liver, muscle and adipose tissue." (PMID 33241460, 2021).
diabetes (continued). "Some clinical studies have reported the association of adiponectin with incident diabetes in subjects with IR, but not in those who were insulin-sensitive." (PMID 34321008, 2021). "Diabetes mellitus is a metabolic disorder characterized by defect in insulin release, insulin working or may be both." (PMID 34903998, 2021). "One of the most promising developments to minimize hyperglycaemia and hypoglycaemia–and, hence, to increase time in range–in individuals with diabetes who require insulin treatment is a closed-loop insulin delivery system (also known as the artificial pancreas)." (PMID 34166426, 2021). "Additionally, the effects of insulin usage in COVID-19 progression are also affected by the blood glucose level and severity of diabetes." (PMID 34367067, 2021). "Diabetes mellitus is a long-term condition that occurs when there are increased levels of glucose in the blood because the body either cannot produce any or enough insulin or cannot effectively use the insulin it produces." (PMID 33505497, 2021). "While replacing insulin alone is a useful treatment for diabetes, the ideal scenario will be replacing the redundant β cells with an alternative treatment that may provide more stable long-term glycaemic control for patients." (PMID 34452145, 2021). "The significant reduction in the frequency of drug-naivety and increase in the use of oral agents or insulin therapy in phase 2 compared to phase 1 (see results section under “Diabetes Mismanagement”) is a validation of this hypothesis." (PMID 34790639, 2021). "It is of great interest to understand insulin and glucose regulation in normal or disease states, which may help discovering therapeutic agents that enhance insulin release from the dormant islets in the setting of type 2 diabetes mellitus." (PMID 34270619, 2021). "Adiponectin can reduce the occurrence and development of diabetes by improving insulin sensitivity." (PMID 34721626, 2021). "It was only after Jean Sterne’s studies in the mid-50s that metformin started gaining the attention it deserved: it was very helpful in treating patients with diabetes diagnosed in adult age, while it was inferior to insulin in treatment of diabetes of young patients." (PMID 35008275, 2021). "Ischemic stroke risk and mortality were highest in diabetes patients treated with insulin and lowest in patients not receiving active pharmacological treatment compared to the general population." (PMID 33478504, 2021). "It is conceivable, but not yet demonstrated penetratingly, that ferroptosis could be significantly diminished by mediating GPX4 with a supplement of Se, playing a role in insulin regulation and diabetes." (PMID 34307381, 2021). "This association of circulating insulin and C peptide with the presence and severity of DR remained highly significant after adjusting for well-known risk factors for DR, including diabetes duration and notably, was independent of glycemic control." (PMID 34912295, 2021). "Based on binary logistic regression, a high non-HDL-C level (odds ratio (OD): 3.338, confidence interval (CI): 1.77–6.28; P < 0.001) and insulin treatment (OR 7.64, CI 1.9–29.3; P = 0.003) were independent predictors of scleroedema in patients with diabetes mellitus." (PMID 33952255, 2021). "Higher resting heart rate in individuals without diabetes was reported to be associated with future unfavorable changes in insulin levels and insulin sensitivity." (PMID 34357115, 2021). "The interplay between insulin and inflammation and between insulin, inflammation, and diabetes is complex and likely influenced by metabolic dysfunction, and therefore, the results of the present study may not generalize to a population of adults with T2DM." (PMID 33691751, 2021).